HMOX2 (heme oxygenase 2)
Description:
[Heme oxygenase 2]: Catalyzes the oxidative cleavage of heme at the alpha-methene bridge carbon, released as carbon monoxide (CO), to generate biliverdin IXalpha, while releasing the central heme iron chelate as ferrous iron. [Heme oxygenase 2 soluble form]: Catalyzes the oxidative cleavage of heme at the alpha-methene bridge carbon, released as carbon monoxide (CO), to generate biliverdin IXalpha, while releasing the central heme iron chelate as ferrous iron.
Synonyms: HO-2
Tractability: Small molecule: a structure with a bound ligand is known; a high-quality ligand is known; it has a high-quality binding pocket. Antibody: its Gene Ontology location is reachable by antibodies, with high confidence; UniProt predicts a signal peptide or a membrane-spanning region. PROTAC: ubiquitination databases record sites on it; its protein half-life has been measured; a small molecule that binds it is known.
Target class: Enzyme; Oxidoreductase
Gene: Protein-coding gene on chromosome 16 (4,474,246 to 4,510,352, forward strand). Ensembl gene ENSG00000103415.
Subcellular location: Microsome membrane; Endoplasmic reticulum membrane
Subcellular location (Human Protein Atlas): Cytosol; Vesicles
Pathways (Reactome):
Cellular responses to stimuli: Cytoprotection by HMOX1
Immune System: Neutrophil degranulation
Metabolism: Heme degradation
Signal Transduction: RHOA GTPase cycle
Transport of small molecules: Iron uptake and transport
Gene Ontology:
Molecular function: heme oxygenase (decyclizing) activity; protein binding; heme binding
Biological process: response to hypoxia; heme catabolic process; heme oxidation; response to oxidative stress
Cellular component: membrane; plasma membrane; endoplasmic reticulum membrane; specific granule membrane
Genetic constraint (gnomAD): Loss-of-function variants: 23 observed, 29.98 expected, observed/expected ratio (o/e) 0.77, 90% interval 0.55 to 1.09. The upper end of that interval is the gene's LOEUF score, 1.09, which puts it in group 4 of 6, group 1 being the genes least tolerant of losing a copy. Missense variants: 374 observed, 394.78 expected, observed/expected ratio (o/e) 0.95, 90% interval 0.87 to 1.03. Synonymous variants: 147 observed, 156.17 expected, observed/expected ratio (o/e) 0.94, 90% interval 0.82 to 1.08.
Homologues: Orthologues: chimpanzee HMOX2 (100% identical), macaque HMOX2 (99% identical), dog HMOX2 (90% identical), rabbit HMOX2 (90% identical), guinea pig HMOX2 (90% identical), rat Hmox2 (90% identical), mouse Hmox2 (89% identical), pig HMOX2 (87% identical), tropical clawed frog hmox2 (59% identical), zebrafish hmox2b (56% identical), zebrafish hmox2a (53% identical), Drosophila melanogaster Ho (20% identical). Paralogues in human: HMOX1 (41% identical).